LINC02898 (long independently transcribed non-coding RNA 2898)
Synonyms: C2orf91
Gene: Long non-coding RNA gene on chromosome 2 (41,935,368 to 41,956,806, reverse strand). Ensembl gene ENSG00000205086.
Diseases named in the same sentence as LINC02898 in open-access papers:
LINC02898 is named in the same sentence as 2 diseases in open-access papers, as found by Europe PMC text mining. Sharing a sentence is not in itself a finding about the gene and the disease.
LINC02898 shares sentences with these, for which no sentence is quoted: breast carcinoma (1 paper); lung adenocarcinoma (1).